NECTIN4 (nectin cell adhesion molecule 4)
Diseases named in the same sentence as NECTIN4 in open-access papers (continued):
Sharing a sentence is not in itself a finding about the gene and the disease.
tumor (continued). "NECTIN4 (65.2%) showed tumor-specific staining, supporting selectivity." (PMID 41261175, 2025). "Similarly, tracers targeting emerging biomarkers, such as Nectin-4 and uPAR, hold potential for improved tumour visualisation and for creating theranostic strategies that combine diagnosis and treatment." (PMID 39858014, 2025). "Furthermore, an important aspect of our study involved the analysis of correlation between Nectin-4 localization and tumor differentiation." (PMID 40699695, 2025). "Significantly higher Nectin‐4 expression was observed in MPUC tumours (P = 0.010), whereas lower expression was found in Sc/NE and SARC variants (P = 0.022 and P = 0.019, respectively) compared to pure NOS tumours." (PMID 39801278, 2025). "On the other hand, in a retrospective study that examined the relationship between the level of NECTIN4 amplification in tumor tissue and prognosis in patients receiving EV monotherapy, nonamplified cases were found to have significantly shorter PFS and OS than amplified cases (p < 0.001)." (PMID 40072062, 2025). "Nectin‐4‐expressing tumours may show varying sensitivity to both EV and platinum‐based chemotherapy." (PMID 39801278, 2025). "This suggests that patients with low primary tumour Nectin‐4 levels might still benefit from EV therapy." (PMID 39801278, 2025). "Our results suggest that in this UC cell line, anti-tumor effects may also be achieved with PPARγ-selective agonists, which may work synergistically with NECTIN4-CAR T cells through surface antigen induction." (PMID 40931013, 2025). "Thus, multiple studies have demonstrated that Nectin-4 is implicated in various aspects of tumorigenesis and progression via the PI3K/AKT pathway, suggesting potential novel strategies for future tumor treatment." (PMID 38606099, 2024). "Non-invasive monitoring of Nectin-4 expression could be beneficial for evaluating tumor progression and guiding treatment." (PMID 38606099, 2024). "Notably, specific immunoreactivity for NECTIN‐4 was detected predominately on cell membrane and cytoplasm of tumour cells, while the surrounding normal tissue was NECTIN‐4 negative." (PMID 39072867, 2024). "The reason may be related to the following factors: first, EV targets on the Nectin-4, which promotes tumor cell proliferation, differentiation, metastasis by activating PI3K/AKT pathway, and plays a role in tumor formation." (PMID 39351347, 2024). "The difference in tumor shrinkage rate between primary and metastatic organs may be explained by the differences in Nectin-4 expression in each organ, and Nectin-4 expression would be different between primary and metastatic organs during EV administration." (PMID 39943993, 2024). "In addition, several studies have confirmed the involvement of Nectin-4 in migration, adhesion, and proliferation of tumor cells." (PMID 38606099, 2024). "In breast cancer, Nectin-4 indirectly activates the Wnt pathway via the PI3K/Akt pathway, and this, in turn, contributes to tumor maintenance by replenishing the pool of cancer stem cells, which is often implicated in treatment failure and tumor relapse." (PMID 39614261, 2024). "We also anticipate from the observed HNSTD in NHP that the recommended therapeutic dose in humans will be sufficient to overcome the sink effect of normal nectin-4 expression while ensuring complete tumor penetration to maximize the cytotoxic effects of exatecan." (PMID 39440991, 2024). "However, other genes regulation involved in anti-tumor immune response and resistance to immunotherapies, NECTIN4, HMGB1, TNFSF18, by CaPa or CaGe seem to be dependent on the cell line used and thus to be more heterogeneous." (PMID 38581044, 2024).
tumor (continued). "In addition to participating in tumor progression, Nectin-4 can mediate drug resistance through the PI3K/AKT pathway." (PMID 38606099, 2024). "However, it has already been demonstrated in other tumour entities within the urological domain that the success of NECTIN‐4‐targeted therapies is dependent upon the expression profile of the target cell, which proves to be both heterogeneous and dynamic." (PMID 39072867, 2024). "Owing to the complexity of tumor cells, contradictory results may be obtained when using mRNA and protein expression levels of Nectin-4 to predict prognosis." (PMID 38606099, 2024). "In the future, EV may be used for the treatment of different tumor subtypes with treatment tailored according to Nectin-4 expression." (PMID 38606099, 2024). "designed an immuno-positron emission tomography (immunoPET) molecular probe targeting Nectin-4 for preclinical evaluation in tumor-bearing mice, based on the finding that Nectin-4 is highly expressed in several cancers with little expression in normal adult tissue." (PMID 38606099, 2024). "In this study, we investigated whether Nectin-4 PET imaging could provide a quantitative assessment of changes in accessible Nectin-4 levels over time and track target engagement at the tumor in response to varying doses of EV." (PMID 39763905, 2024). "As expected, the presence of a nectin-4–expressing tumor mass constituted a sink for ETx-22." (PMID 39440991, 2024). "In contrast, on tumor cells expressing much higher levels of nectin-4, the avidity of 15A7.5 might ensure proper binding and internalization." (PMID 39440991, 2024). "Furthermore, employing imaging systems, we scrutinized the swift diffusion and heightened tumor uptake of Nectin-4 NDC in vivo." (PMID 38755613, 2024). "EV is thought to have anti-tumor activity by targeting cells that express Nectin-4." (PMID 37091148, 2023). "Repeated monitoring of circulating Nectin-4 protein or Nectin-4 expression in circulating tumor cells might be a useful biomarker during EV treatment." (PMID 37174031, 2023). "We recently established an immunocompetent mouse model by transplanting human nectin-4-introduced mouse cancer cells and found that intratumoral rMV-SLAMblind treatment activated natural killer (NK) cells and elicited a tumor antigen-specific CD8 T cell response in the tumor microenvironment." (PMID 37875555, 2023). "One of them is BT7480—Bicycle tumor-targeted immune cell agonistTM targeting nectin-4 and CD137." (PMID 37568798, 2023). "The fact that in 2019, the American FDA (Food and Drug Administration) approved the use of a cancer drug conjugate with a monoclonal antibody directed against nectin-4 in the treatment of metastatic urothelial cancer opens up possibilities for its potential application in different neoplasms." (PMID 37958883, 2023). "Immunohistochemical analysis of the tumor specimens exhibited increased nectin-4 expression." (PMID 38023224, 2023). "The anti-Nectin-4 monoclonal antibody in enfortumab vedotin specifically binds to Nectin-4 on the cancer cells’ surface, allowing for the selective delivery of the cytotoxic agent to the tumor site." (PMID 37686503, 2023). "The mRNA and protein levels of nectin-4 were markedly higher in the tumor than in adjacent tissues." (PMID 37568798, 2023). "Furthermore, the decreased amount of CD8+ tumor-infiltrating lymphocytes in patients with EC and MSH deficiency or Nectin-4 overexpression is thought to provide important clues for screening and monitoring patients responding to cancer immunotherapy." (PMID 37345201, 2023). "Thus, tumor expression of Nectin-4 before EV treatment can be a useful predictive factor for preferable outcomes." (PMID 37174031, 2023). "Furthermore, the enlarged cell morphology induced by senescence-inducing stimuli was efficiently inhibited by siRNA-mediated depletion of Nectin-4 in both tumor and normal cells." (PMID 38062106, 2023).
tumor (continued). "More advanced TNM and greater tumor thickness correlated with high expression of nectin-4." (PMID 37568798, 2023). "Additionally, in some patients where tissue from a metastatic site was available Nectin-4 expression was decreased in the metastatic site compared to the primary tumor." (PMID 36686762, 2022). "We did not observe an association of Nectin-4 expression with tumor stage, lymph node involvement or grading." (PMID 36268557, 2022). "Immunohistochemical staining showed variable expression of NECTIN4 in tumor cells." (PMID 35256687, 2022). "This underscores that Nectin-4 is the more reliable tumor marker." (PMID 36497350, 2022). "Therefore, to study intra-entity heterogeneity of NECTIN4 protein expression, independent biopsies of the same tumor entity, taken from distinct locations in the urinary bladder of HR NMIBC patients with multifocal disease, were analyzed." (PMID 35484425, 2022). "In our study, the high frequency of canine Nectin‐4 expression suggested the possibility that nectin‐4 may be a useful tumour marker." (PMID 35905293, 2022). "Nectin‐4 is a cell adhesion molecule and expressed in several tumor cells." (PMID 35905293, 2022). "The high proportion of Nectin-4 positive pRCC tumors, however, raises the question whether the use of Nectin-4 directed therapies could add to the armamentarium of agents in this rare tumor entity." (PMID 36136143, 2022). "In a multivariable Cox regression model Nectin-4 expression was also a significant marker for survival when adjusting for tumor stage, lymph node metastases and p16 (p-value model p = 0.006, Hazard rate Nectin-4 0.418, regression coefficient −0.969, p = 0.041)." (PMID 36268557, 2022). "It is necessary to analyze whether the expression of Nectin‐4 in canine CPLA is involved in tumour growth, as in human Nectin‐4‐expressing tumours." (PMID 35905293, 2022). "A recent study using fusion protein demonstrated the relationship between TIGIT and Nectin4, which is composed of the Fc part of human IgG1 and the extracellular part of a variety of tumor markers, including Nectin4, then stained NK cells to confirm that Nectin4 is a TIGIT ligand." (PMID 35720417, 2022). "Overexpression of Nectin-4 has already been shown for a variety of tumor entities." (PMID 36497350, 2022). "However, there was a significant positive correlation between Nectin‐4 expression and tumour volume (r = 0.623, p < 0.05) and tumour weight (r = 0.735, p < 0.05)." (PMID 35905293, 2022). "Moreover, intra-entity-specific heterogeneity of NECTIN4 protein expression was considered by analyzing independent biopsies of the same tumor entity, taken from distinct locations in the urinary bladder of HR NMIBC patients with multifocal disease." (PMID 35484425, 2022). "Additionally, we observed a significant reduction in NECTIN4 protein expression in stroma-invasive tumor areas compared to matched non-invasive areas of the same CIS/T1HG and pure TaHG/T1HG tissue samples, respectively." (PMID 35484425, 2022). "The PTA designed here (mAbNectin-4-ICG) could be combined with the NIR imaging system to undoubtedly provide an intraoperative navigation platform for the precise resection of Nectin-4-overexpressing tumor tissues (primary or metastatic tissue)." (PMID 35614462, 2022). "Anti-angiogenic therapy has recently attracted attention as a novel therapeutic strategy; thus, targeting NECTIN4 may also contribute to tumor suppression by preventing angiogenesis." (PMID 35256687, 2022). "Moreover, increased median NECTIN4 protein levels were noted in LG tumor areas when comparing LG to matched HG tumor samples of mixed-grade lesions (P < 0.01)." (PMID 35484425, 2022). "In addition, there were cases with high Nectin‐4 expression and large tumour volumes that survived for a long time after surgical resection." (PMID 35905293, 2022).
tumor (continued). "The self-renewal properties of circulating cancer cells induced by Nectin-4 expression are considered responsible for tumor aggressiveness and may play a role in EMT–TME transitions." (PMID 36553083, 2022). "The proportion of NECTIN4-positive tumor cells varied among patients, ranging from 0 to 100%." (PMID 35256687, 2022). "Strikingly, we found that more patients in the high expression group (16/19, 84.2%) exhibited tumor metastasis compared with the low expression group (18/34, 52.9%), which implies that Nectin-4 might regulate the tumor progression in OS." (PMID 35953862, 2022). "Since NECTIN4 also contributes to the viability and proliferation of tumor cells, inhibition of NECTIN4 itself might be another way to utilize NECTIN4 as a therapeutic target." (PMID 33808400, 2021). "Skin toxicity instead may be at least partially classified as on-target/off-tumor toxicity, being nectin-4 highly expressed by cutaneous cells." (PMID 33509252, 2021). "Interestingly, in the model P8X20, the expression level of 7 markers (i.e., Ki67, KRT5/6, KRT20, 34βE12, PD-L1, EGFR, and Nectin4) was exactly similar between the patient tumor and the next generations." (PMID 35432811, 2021). "NECTIN4 is known to be highly expressed in several tumors and enhances tumor progression." (PMID 33808400, 2021). "It remains unknown whether circulating tumor cells proliferate in blood, but the present results raised the possibility that the T47D cells stably expressing both nectin-4 and p95-ErbB2 not only survive but also proliferate in blood." (PMID 33795719, 2021). "Positive NECTIN4 staining was mainly found in the cytoplasm and on the membranes of tumor cells." (PMID 32824340, 2020). "Interestingly, NECTIN4 is overexpressed in some epithelial cancers, and its overexpression is correlated with tumor progression and patient outcome." (PMID 32824340, 2020). "Tumor expression levels of Nectin-4 and PD-L1 were evaluated." (PMID 33019653, 2020). "In the entire cohort, strong Nectin-4 expression was not an independent predictor of cancer-specific mortality, but it tended to be associated with a higher risk of tumor progression." (PMID 32751328, 2020). "Furthermore, pre-screening of tumor biopsy samples in this study identified high levels of Nectin-4-positive UC cells." (PMID 31444589, 2020). "Taken together, our present data unveiled that Nectin-4 played a crucial role in tumor biology, and it could serve as a useful prognostic predictor of human EC." (PMID 31043861, 2019). "This would explain the better association between high Nectin-4 expression and its association with lower tumor stage and absent lymph node involvement." (PMID 31572728, 2019). "Our present data unveiled that Nectin-4 played an important role in tumor biology and could serve as a useful prognostic predictor of human EC." (PMID 31043861, 2019). "In the tumor model established using TE-1 cells, the tumor growth curves showed that knockdown expression of Nectin-4 significantly inhibited the tumor growth (P < 0.001), while the tumor growth of Nectin-4 over-expression group also trended to be faster than that of control group (P = 0.1816)." (PMID 31043861, 2019). "Several reports identified Nectin-4 as a new promising tumor antigen in various carcinomas." (PMID 31572728, 2019). "The intervention of Nectin-4 expression in EC cell lines could regulate the cell viability as well as the abilities of migration, invasion and tumor formation." (PMID 31043861, 2019). "Our present data also showed that increased Nectin-4 expression could significantly enhance the cell proliferation in vitro and tumor growth in vivo." (PMID 31043861, 2019). "Therefore Nectin 4 protein expression was correlated to omics and medium dimensional data derived from tumor tissues, the ascites, and the serum of the patients by various statistical approaches, like pathway, network, and gene-set analyses." (PMID 31137558, 2019).
tumor (continued). "One possible explanation could be that Nectin-4 expression on the cancer cell surface is highly present during tumor formation, but declines during progression." (PMID 31572728, 2019). "In the tumor model established using Eca-109 cells, the tumor growth curves showed that knockdown expression of Nectin-4 significantly inhibited the tumor growth (P < 0.0001), while the tumor growth of Nectin-4 over-expression group also trended to be faster than that of control group (P = 0.0831)." (PMID 31043861, 2019). "The intervention of Nectin-4 expression in EC cell lines showed that the increased Nectin-4 expression could significantly promote the cell viability, migration, invasion and tumor formation." (PMID 31043861, 2019). "This molecule is highly expressed in embryo- and placenta-derived tissues, but the normal distribution of nectin-4 in adult tissues is limited to the trachea, the appendix, and the placenta, and its expression in the lung is very low and has been shown to be a tumor marker." (PMID 29743202, 2018). "Only the human tumor cell marker Nectin-4/PVRL4 made cells permissive to MeV." (PMID 27657109, 2016). "Data suggested that Nectin-4 might play functionally important roles in tumor progression and metastasis independently of the TNM classification." (PMID 25888293, 2015). "In particular, there are only limited studies on Nectin-4 in tumor biology and clinical cancers." (PMID 25888293, 2015). "Besides these clinical studies, several recent basic studies have revealed that the potential roles and functions of Nectin-4 in tumor biology." (PMID 25888293, 2015). "Interestingly, the patients with Nectin-4 high tumor had significantly poorer postoperative prognosis than patients with Nectin-4 low (P = 0.013, Log-rank test)." (PMID 25888293, 2015). "Although the accumulating evidence indicates that Nectin-4 may play a critical role in tumor biology, the precise roles of Nectin-4 in tumor progression and metastasis in human cancers are not fully elucidated." (PMID 25888293, 2015). "Therefore, more marker genes like for example MMP13, UBE2Q2, Nectin-4 or ALDH will have to be tested for their ability not only in tumour cell detection but also in tumour cell characterization." (PMID 24202442, 2013). "Finally, Nectin-4 is shed from the tumor cell surface and represents a sensitive, reliable, and complementary serum marker for the follow-up of patients with metastatic breast carcinoma." (PMID 17474988, 2007). "In addition to the observed cytoplasmic staining of cancer tissue predominantly with the adhesion molecule Nectin-4, in our further research, we determined stronger expression of both Nectins at the invasive edges of the tumor, although it was much weaker with Nectin-2." (PMID 40699695, 2025). "Interestingly, the authors observed significantly higher Nectin‐4 expression levels in primary tumours compared to metastatic sites, which may have a further impact on therapy response rates." (PMID 39801278, 2025). "Additionally, on-target off-tumor toxicity may occur when the target antigen is expressed at low levels in healthy tissues, as observed with Nectin-4 in the urothelium, leading to cutaneous and ocular side effects." (PMID 41184856, 2025). "Additionally, in their study, nectin-4 expression was also found to correlate with tumor size." (PMID 40244005, 2025). "Finally, we explore the anti-tumor activity of NECTIN4-CAR T cells in an EV-resistant UC model." (PMID 40931013, 2025). "Furthermore, we confirmed the correlation of NECTIN4 CNVs, mRNA, and protein expression in a The Cancer Genome Atlas (TCGA) pan-cancer analysis and explored the prevalence of NECTIN4 CNVs representing a potential tumor-agnostic genomic biomarker to predict EV response in multiple cancer entities." (PMID 38657187, 2024). "Moreover, Nectin-4 NDC exhibited noteworthy dose-dependent anti-tumor efficacy in in vivo studies." (PMID 38755613, 2024).